ICAM1 (intercellular adhesion molecule 1)
Diseases named in the same sentence as ICAM1 in open-access papers (continued):
Sharing a sentence is not in itself a finding about the gene and the disease.
cancer (continued). "Beyond that, the role of neoplastic ICAM-1–FG interaction in regulating malignant tumor cell growth is still largely unknown." (PMID 39168965, 2024). "Interestingly, most genes were up-regulated in multiple groups; genes for chemokines (Ccl2, Ccl5), cell adhesion (Icam1, Lgals3) and a growth factor (Ngf) were up-regulated in at least three non-cancer groups." (PMID 39254423, 2024). "Moreover, EGF secreted by TAMs increases the expression of αMβ2 integrin in TAMs and ICAM-1 in cancer cells to facilitate adhesion between TAMs and cancer cells." (PMID 39513610, 2024). "Overwhelming ICAM-1 restrained cancer invasiveness in different models." (PMID 39050471, 2024). "In addition, the expression of ICAM1 is considered an inflammatory marker in cancer and is related to the migratory, invasive, and metastatic capacity of the many types of cancer cells." (PMID 39201551, 2024). "ICAM1 overexpression is correlated with reduced recurrence-free and overall survival in HGSOC, and is a STAT1-associated gene with known correlation with disease metastasis in several cancers, including serous papillary endometrial cancer." (PMID 38254014, 2024). "A major complication of HCC is portal vein tumor thrombus (PVTT), and it was shown that lncRNA ICR (ICAM-1-related) was expressed in Intercellular adhesion molecule 1 (ICAM-1)-positive cancer stem cells (CSCs) regulating CSC function and leading to PVTT development." (PMID 38203767, 2024). "Notably, TBMS1-treated VECs expressed lower levels of the adhesion molecules VCAM-1 and ICAM-1, which were involved in cancer cell intra/extravasation." (PMID 38230220, 2024). "As mature exosomes are enriched in ICAM‐1 and MHC class II proteins, DCs could transfer functional MHC–peptide complexes and ICAM‐1 to other immune cells through secreting exosomes which play an important role in triggering effector T‐cell responses in cancer." (PMID 39611045, 2024). "Wnt/β-catenin may also promote cancer cell migration and invasion by inducing the expression of transfer-related proteins such as intercellular adhesion molecule-1 (ICAM-1) and matrix metalloproteinases (MMPs)." (PMID 40028002, 2024). "Impaired ICAM1-mediated cancer cell-T-cell adhesion and interaction might lead to paucity of T cells in the TME." (PMID 36871040, 2023). "Therefore, it makes sense that PD-L1 and ICAM-1 correlatedly expressed in gene-expression and gene-immunotherapeutic efficacy in patients with cancers." (PMID 36688994, 2023). "The results reveal that the combination was most effective in decreasing cellular oxidants and increasing glutathione levels, while there was a significant decrease in cancer cell migration and invasion involved in the suppression of iNOS, ICAM-1, and MMP-2 proteins." (PMID 37575276, 2023). "Whether ICAM-1 expression benefits a cancer more than it benefits the host immune system appears dependent on the cancer type and other contextual factors." (PMID 37237555, 2023). "One other such signaling molecule is ICAM1, which is localized at the cell surface as a receptor glycoprotein, and several studies have identified ICAM1 as a key signaling molecule contributing to cancer cell proliferation, migration, invasion, and neovascularization." (PMID 37190316, 2023). "Thus, CD44 and ICAM1 both have been studied extensively as selective therapeutic targets in the field of cancer therapy and prevention." (PMID 37190316, 2023). "Next, we investigated whether CT26 and 4T1 cancer cells have different expression levels of ICAM‐1 on their cellular surfaces." (PMID 37097643, 2023). "Importantly, STARs would remain susceptible to immune evasion by cancer cells losing expression of CD58 and/or ICAM-1." (PMID 36598945, 2023). "ICAM1 emerged as the most frequently differentially expressed gene, indicating that ICAM1 in cancer cells might play a critical role in regulating cell–cell adhesion with T cells." (PMID 36871040, 2023).
cancer (continued). "Furthermore, there were 42.5% of patients with iCCA and 29.0% with eCCA carrying ICAM1+ cancer cells, among 78 CCA patients." (PMID 37717087, 2023). "LKB1 mutant cancer cells result in marked suppression of intercellular adhesion molecule-1 (ICAM1)." (PMID 36871040, 2023). "Indeed, we observed the positive correlation between CD8+ T-cell infiltration and the expression levels of LFA-1 or ICAM-1 in certain types of human cancers in TCGA." (PMID 37605139, 2023). "Deciphering the roles of ICAM-1 is an aim of current research in many cancer fields." (PMID 37237555, 2023). "Finally, we assessed the correlation between the ICAM1 expression and the survival of ICIs-treated cancer patients." (PMID 36871040, 2023). "Multiple cell adhesion molecules and tight junction proteins that confer epithelial-like traits, such as plakoglobin, ICAM1, and CD44, have been identified to underlie the outperforming attributes of CTC clusters in cell survival, cancer stemness, and immune invasion." (PMID 36991428, 2023). "Next, we explored the in vivo role of ICAM‐1 in an anti‐PD‐1‐treated mouse cancer model." (PMID 37097643, 2023). "Importantly, the CCA-specificity of ICAM1 is higher than many common cancer targets such as ROR1, HER2, EGFR, VEGFR, and P-selectin." (PMID 37717087, 2023). "Second, ICAM-1 partially mediates the invasive and metastatic potential of cancer cells." (PMID 35630004, 2022). "IL-6 plays a critical role in metastasis of cancer cells by modulating ICAM-1 expression." (PMID 36505809, 2022). "While ICAM-1-mediated endo- and transcytosis of drugs is suitable for cancer treatment, we aimed to generate ICAM-1-specific nanobodies that remain bound to the epithelial cell surface in order to immobilize captured allergens and prevent their uptake through the mucosal barrier." (PMID 36439110, 2022). "Different expression levels of ICAM1 have been found in various malignant tumors." (PMID 36353618, 2022). "Several of the most often used cancer stem cell markers in the recruited studies, including ICAM-1, CD133, CD90, CD44, CK19, and Nanog, were evaluated to determine whether CCSCs may possibly be employed for HCC prognostic prediction." (PMID 35884432, 2022). "Therefore, we measured the migration/invasion ability of cancer cells according to ICAM-1 expression using either Matrigel-uncoated or Matrigel-coated transwell chamber." (PMID 35487888, 2022). "We propose that phosphorylated ICAM-1 as an adapter protein may modulate cancer malignancy by further promoting the activity of SRC on the c-MET-SRC axis." (PMID 35487888, 2022). "ICAM1 has been reported to mediate adhesion-dependent cell–cell interactions and to play an important role in regulating the size of tumors and the spherical sizes of cancer cell lines in vivo and in vitro." (PMID 35619172, 2022). "The high expressions of Axl, Tim-4, CD31, IDO1, ICAM1, and PD-L1 were associated with the high ESTIMATE score and immune score, while the high expressions of Axl, Tim-4, and CD31 were associated with the high stromal score in many types of cancers." (PMID 36059952, 2022). "ICAM-1 is expressed by many different types of cancer cells and may play an important role in the adhesion of CTCs on the endothelium, resulting in enhancing the extravasation of CTCs." (PMID 35888601, 2022). "We observed that ICAM-1 was expressed by both cancer and endothelial cells." (PMID 35630004, 2022). "In addition, the interaction between LFA-1 and ICAM-1 is involved in inflammatory responses, inflammatory pathologies, autoimmune diseases, and many cancer processes." (PMID 36016615, 2022). "ICAM-1 - Lymphocyte Function-associated Antigen 1 (LFA-1) is a pair of classical adhesion molecules that affect cell-cell interactions, especially in formatting immunological synapses between cancer and T cells." (PMID 36085295, 2022).
cancer (continued). "In addition, analyzing malignant B cells from chronic lymphocytic leukemia patients our data indicated that the percentage of activated CD20 CAR T cells was positively correlated with the amount of ICAM-1 on cancer cells." (PMID 36189315, 2022). "Parsimony diagram for the progression of cancer by MTCAF-derived ICAM1." (PMID 36016615, 2022). "In addition, miR-222 and miR-339 have also been shown to bind 3’UTR of ICAM-1 promoter to suppress the ICAM-1 expression and promoted resistance of cancer cells to CTLs." (PMID 36505809, 2022). "ICAM-1 expression in cancer cells was the score with the high-score method with a median expression level of 20 (range 0 to 200); 43 cases (91.48%) were scored as 1+ (median expression level of 20 range 5–90) and four (8.52%%) as 2+ (median expression level of 80 range 60–100)." (PMID 35630004, 2022). "In this work, we show that the incubation of macrophages with cyH increased their ability to induce pro-inflammatory cytokine expression and secretion in ECs and ICAM1 expression in ECs and to shift EC phenotype toward one allowing the adhesion of monocytes and cancer cells." (PMID 36248978, 2022). "Indeed, EC ICAM1 is involved in cancer cell adhesion and extravasation of several cancer cell types, which are two needed steps for the metastatic spread of cancer cells." (PMID 36248978, 2022). "Chimeric antigen receptor (CAR)-T cell therapy has shown remarkably effective in cancer treatment and ICAM-1 could be a promising target for CAR-T cells." (PMID 36505809, 2022). "The mechanism of sICAM-1 production is unclear, but it may be produced by proteolytic cleavage of membrane-bound ICAM-1, and released from the local cancer cell and enter the serum." (PMID 36505809, 2022). "Using an antibody screen to identify the origin of this differential CAR T cell responsiveness, ICAM-1 was found to be highly expressed at the surface of the Raji B lymphoma cell line whereas in two different carcinoma cell lines (BxCP3 and EGI-1) the surface expression of ICAM-1 was very low." (PMID 36189315, 2022). "Thus, their prognostic value for other diseases is less clear, but the emerging role of VCAM-1 in several neurological disorders and cancers has been emphasized, as has the role of ICAM-1 in psychiatric disorders and peripheral immune system." (PMID 33803155, 2021). "It has been previously reported that the expression of ICAM-1 on human cancer cells could regulate the adhesion between NK cells and target cells through its binding with lymphocyte function–associated antigen 1 (LFA-1) on NK cells." (PMID 33462208, 2021). "TNF-α expression was observed to upregulate expression of several cancer-associated genes in the epithelial cells which include extracellular matrix (ECM) remodeling genes such as MMP9, PLAU, FN1 and ICAM1, chemokines such as CCL2, CXCL2, CXCL3 and CXCL10 and regulatory genes such as UBD and PTGS2." (PMID 34946170, 2021). "To determine if the presence of cancer cells arrested in the MVNs could induce local activation of ECs, we used high-resolution confocal microscopy to visualize ICAM-1 in the vicinity of arrested MDA-MB-231 cells after 6 h." (PMID 33637851, 2021). "Similarly, the treatment of human esophageal adenocarcinoma cells with sPLA2 inhibitor attenuates the expression of ICAM-1 and decreases viability and proliferation of this type of cancer cell." (PMID 34208346, 2021). "Additionally, GM-4-53 reduced the expression of Intercellular adhesion molecule 1 (ICAM-1), which is a driver of cell migration via the docking and trafficking of leukocytes toward cancer and stromal cells." (PMID 34299315, 2021). "Although reported studies in the literature as well as our own observations all showed positive impact on cancer-specific drug delivery mediated by ICAM-1, the ICAM-1-related adverse effects need to be further studied with different time frames, various doses, and function-specific assays." (PMID 35056985, 2021).
cancer (continued). "Co-culture of melanoma cells with endothelial cells composing the abluminal surface of blood vessels, was demonstrated to induce the expression of genes linked to cancer cell migration (CCL2, ICAM1), cancer progression (TRAF1, SERPINB2) or stem cell properties (PDGFB; CFDP1)." (PMID 34604096, 2021). "Furthermore, in both of the cancer cell lines, ND caused an increased level of IL-8 and a decreased level of TIMP-2, whereas GO caused only decreased levels of TIMP-2 and ICAM-1 proteins." (PMID 34829982, 2021). "ICAM-1 knockdown decreased macrophages recruitment into carcinomas in vivo." (PMID 34368156, 2021). "Notably, CD54 (ICAM-1) expression on cancer cells is essential for NK cell cytotoxicity, and its magnitude directly correlates with OS susceptibility to NK cell lysis." (PMID 33322371, 2020). "Expression of VCAM-1 and ICAM-1 seems to be closely related to the metastasis of cancer cells." (PMID 33103723, 2020). "Studies have shown that CD44 and ICAM1 are cancer stem cell markers in ESCC." (PMID 31438645, 2019). "By analogy with human cancer cells, overexpression of ICAM‐1 may play a role in metastasis (Yu, Lin, & Tang, 2013)." (PMID 30370674, 2019). "Similarly, it was indicated that ICAM-1 and ICAM-2 suppression was positively correlated with decreased leukocyte extravasation and associated with cancer development." (PMID 31877723, 2019). "It was previously shown that IFNs regulate expression of MHC, ICAM-1 and PD-L1 in cancer cells." (PMID 31552026, 2019). "In order to investigate whether same phenomenon is observed in PCa patients, the relationship between ICAM1 expression and patients with malignant PCa was analyzed." (PMID 31619256, 2019). "Also, PNEE reduces the protein levels of integrin-1 in HCT-116 and E-selectin and intercellular adhesion molecule-1 (ICAM-1) in endothelial cells EA.hy926, which reduces the adhesion ability of cancer cells." (PMID 31636686, 2019). "Interference of carbenoxolone in cancer colonization was found to be mediated by impairment of cell adhesion via reduction of intercellular adhesion molecule 1 (ICAM1) expression levels, thus diminishing cell-cell interactions and cellular adherence to the extracellular matrix (ECM)." (PMID 31533288, 2019). "This suggests that ICAM-1 needs an on-off switch for cancer progression and metastasis." (PMID 31297450, 2019). "Likewise, we identified that ICAM-1 expression is attenuated in metastatic cancer cells compared to primary cancer cells." (PMID 31297450, 2019). "In addition, the activation of NF-κB associates with the upregulation of cell proliferation enhancers (e.g., cyclin D1 and c-myc), cell adhesion molecules, and several angiogenesis factors enhance cancer cell engraftment (e.g., ICAM-1 and VEGF)." (PMID 31163672, 2019). "NF-κB signaling may also participate in cancer invasion and metastasis by inducing the expression of adhesion molecules, such as intercellular adhesion molecule-1 (ICAM-1) and vascular cell adhesion molecule-1 (VCAM-1), and metalloproteinases (MMPs)." (PMID 30166456, 2018). "The expression of ICAM1 is elevated in many human cancers, including PTC." (PMID 30414611, 2018). "Therefore, the type of cancer to be treated with ICAM-1 blocking mAbs should be carefully selected based on its expression of ICAM-1." (PMID 30258446, 2018). "Given that the primary objective of this study was to use the SIN for generating expanded populations of functional T-cells, we tested the effect of substrate-immobilized CCL21 + ICAM1 on the capacity of the expanded cytotoxic T-cells to kill ovalbumin-expressing cancer cells." (PMID 29942308, 2018).
cancer (continued). "Interestingly, some clinical trials have been initiated to target ICAM-1 and TGFβ2 individually as the possibilities for future cancer immunotherapies." (PMID 29966014, 2018). "Moreover, CCL2 induces the expression of ICAM1 on human lymphatic endothelial cells and facilitates the attachment of cancer cells to lymphatic endothelial cells." (PMID 30585203, 2018). "Because the membrane-bound adhesion molecule ICAM-1 may serve as a preferential target for immune-cancer therapies, its potential role in the CAF-dependent onset of a proinvasive ECM remodeling was further analyzed." (PMID 27901489, 2017). "In addition, secreted soluble ICAM1 (sICAM1) was shown to play a role in cancer invasion and metastasis." (PMID 28827764, 2017). "Increased ICAM-1 stability results in increased metastasis and invasiveness of cancer cells." (PMID 29137327, 2017). "ICAM-1 expression may enable malignant progression via ERK signaling, which likely regulates cancer progression by modulating ICAM-1 stability." (PMID 29137327, 2017). "Furthermore, exosomes bearing ICAM-1 that are produced by cancer cells can block adhesion of leukocytes to endothelial cells." (PMID 29099772, 2017). "Furthermore, ICAM-1 level was significantly higher in metastatic and advanced cancer cells/tissues (MDA-MB-231) than in normal epithelial cells (MCF10A)." (PMID 29137327, 2017). "ICAM-1 also promotes metastasis and is correlated with the progression of other cancers." (PMID 28903329, 2017). "ICAM-1 plays a vital role in leukocyte adhesion and cancer cell invasion." (PMID 28903329, 2017). "Among adhesion molecules, ICAM-1 is upregulated in response to a number of stimuli, and several lines of evidence have shown that, in addition to its role in leukocyte adhesion and cancer cell invasion, ICAM-1 also plays a role in IL-6-mediated OS cell motility." (PMID 27851822, 2016). "Cancer cell can expresses and release soluble ICAM1, that is regulated by TNF-α and INF-γ." (PMID 28105922, 2016). "Therefore, inhibition of these adhesion molecules, particularly ICAM-1, has great potential in the treatment of advanced stage cancers." (PMID 26823953, 2016). "Increased levels of ICAM1 were reported in several human malignances and cancer cell lines." (PMID 28105922, 2016). "Evidence showed that miR-339 was up-regulated in HNE-treated leukemic cells and could suppress ICAM-1 expression in cancer cells." (PMID 27036025, 2016). "An increased ICAM-1 cell surface expression may improve cancer cell recognition by the host effector cells." (PMID 26087182, 2015). "Exposure to exogenous TNFα can induce ICAM1 in cancer cells." (PMID 25879517, 2015). "Because recent studies have also indicated that ICAM-1 plays a key role in cancer cell migration and invasion, ICAM-1 may be involved in the AREG-induced migration." (PMID 26503469, 2015). "It has been reported that overexpression of ICAM1 protein correlates with cancer prognosis." (PMID 25879517, 2015). "Noteworthy, both neutralizing ICAM-1 antibody and isotype control antibody did not alter the celecoxib-induced loss of cancer cell viability as assessed by WST-1 analysis (data not shown)." (PMID 26513172, 2015). "ICAM-1 also promotes the migration of other cell types, including cancer cells." (PMID 26231039, 2015). "ICAM-1 is an adhesion molecule that is involved in cancer metastasis." (PMID 26503469, 2015). "ICAM-1 is a potent metastatic factor that mediates cancer migration and metastasis." (PMID 24398980, 2014). "Moreover, a detailed analysis of the distribution of rupture forces suggests that ICAM-1 interacts preferentially with one ligand on T24 cancer cells and with two ligands on J82 cancer cells." (PMID 24857933, 2014). "Many studies have reported a relationship between ICAM1 and cancer." (PMID 25521548, 2014).